SYVN1 (synoviolin 1)
Diseases named in the same sentence as SYVN1 in open-access papers (continued):
Sharing a sentence is not in itself a finding about the gene and the disease.
lung squamous cell carcinoma (1 paper, 2023). "Consistently, IHC staining demonstrated that LUAD tissues with high pathological grade exhibited much higher SYVN1 levels; moreover, SYVN1 was also overexpressed in lung squamous cell carcinoma compared with adjacent normal tissues." (PMID 37816756, 2023). "Next, the overall survival rates of LUAD and lung squamous cell carcinoma were evaluated according to SYVN1 and MCT4 expression independently using The Cancer Genome Atlas (TCGA) datasets." (PMID 37816756, 2023). "According to the intensity and density of positive cells, the IHC staining results indicated that the expression of SYVN1 was associated with pathological grading in LUAD but not in lung squamous cell carcinoma." (PMID 37816756, 2023). "The positive rate of SYVN1 expression in LUAD and lung squamous cell carcinoma was significantly higher than that in adjacent normal tissues." (PMID 37816756, 2023). "Kaplan‒Meier analysis indicated that high SYVN1 expression is correlated with poor overall survival in LUAD and lung squamous cell carcinoma based on our samples and data obtained from the KM plotter website." (PMID 37816756, 2023).
memory impairment (1 paper, 2025). "Our results demonstrate that ELK1 aberrantly increases in AD and genetic or pharmacological inhibition of ELK1 can alleviate AD-related pathology and memory impairments by enhancing the SYVN1-mediated PS1 ubiquitination and degradation, indicating that ELK1 may be a novel target for AD treatment." (PMID 40307574, 2025).
non-small cell lung carcinoma (1 paper, 2024). A group of at least three distinct histological types of lung cancer, including non-small cell squamous cell carcinoma, adenocarcinoma, and large cell carcinoma. "SYVN1 promotes non-small cell lung cancer metastasis by blocking autophagy-mediated MIEN1 degradation." (PMID 38679705, 2024).
papillary thyroid carcinoma (1 paper, 2024). "This study aimed to investigate SYVN1’s roles and molecular pathways in papillary thyroid cancer (PTC)." (PMID 38679705, 2024).
tumor (34 papers, 2013 to 2026). "Since SYVN1 is strongly linked to tumour metabolic reprogramming and to increased lactate efflux from LUAD cells, investigating the role of SYVN1 in tumour progression is important." (PMID 37816756, 2023). "Additionally, clinical data analysis revealed that increased SYVN1 levels were associated with larger tumor sizes, lower blood NK cell proportions, and greater microvascular invasion." (PMID 37099251, 2023). "In cancers of the breast and ovary, SYVN1 inhibits tumor progression by promoting the ubiquitination of substrate proteins, such as PFAK, CPT2, and SLC7A11, which can lead to either their degradation or stabilization." (PMID 40877231, 2025). "This includes elucidating how SYVN1 operates differently in various tumors and its dual roles in processes such as metastasis and invasion within the same tumor." (PMID 40877231, 2025). "Mechanistically, circSIRT5 exerted its tumor-suppressive activities through the formation of a ternary complex involving circSIRT5, SYVN1, and PHGDH." (PMID 39223162, 2024). "With regards to SYVN1, previous studies have shown that it functions as a tumor suppressor in breast and ovarian cancers." (PMID 37766871, 2023). "SYVN1 has also been proved to promote the growth of tumor cells by promoting the ubiquitination and degradation of tumor suppressor SIRT2." (PMID 37280656, 2023). "The xenograft tumors derived from SYVN1-knockdown HCC cells exhibited smaller tumor size, volume and weight, compared with control group." (PMID 37099251, 2023). "Partial least-square-discriminant analysis (PLS-DA) was performed, which revealed an obvious separate metabolic trend in tumour samples compared to the SYVN1 knockdown and control samples." (PMID 37816756, 2023). "It is well established that E3 ligases, including SYVN1 can have opposite effects as either tumor suppressors (TS) or oncogenes depending on the context or type of cancer." (PMID 37766871, 2023). "First, IHC analysis was performed to classify these tumours into two groups with low and high SYVN1 levels." (PMID 37816756, 2023). "Biologically, SYVN1 knockdown successfully compromises cell proliferation and tumour xenograft growth in mouse models that can be partially rescued by overexpression of MCT4." (PMID 37816756, 2023). "Taken together, silencing SYVN1 in oncolytic adenovirus-infected tumors seemed to bring about a more immediate and possibly more effective tumor growth control." (PMID 36499754, 2022). "Inhibition of circ-SOX5 increased the apoptosis of tumor cells and reduced the proliferation of tumor cells through miR-502-5p/SYVN1 axis." (PMID 35048790, 2022). "Some studies have shown that SYVN1 is related to the development of various tumors, and SYVN1 promotes the proliferation of tumor cells in HCC." (PMID 35048790, 2022). "This revealed a trend towards more effective tumor growth control by the SYVN1-silencing oncolytic adenovirus." (PMID 36499754, 2022). "As we had envisioned, silencing SYVN1 did promote adenovirus-mediated A549 cell killing in vitro and A549 tumor growth inhibition in vivo." (PMID 36499754, 2022). "Mechanistically, KDM4D/SYVN1/HMGB1 axis modulates the tumor growth, migration and self-renewal features via promoting accumulations of HMGB1." (PMID 34820329, 2021). "Similarly, in our collected tumor tissues, we observed high expression levels of SYVN1 and EGFR in tumor tissues and a positive correlation between their expression." (PMID 40877231, 2025). "In this work, based on various cohorts, we assessed the correlations between GLUD1 with IL-32 gene expression levels in HCC tissues, between SYVN1 and LASP1 gene expression levels in HCC tissues, and between GLUD1 gene expression level and tumor size in HBV-associated HCC." (PMID 38587834, 2024). "In addition, SYVN1 effectively impairs cell proliferation, migration, invasion, and the formation of tumor xenografts in mice models." (PMID 38679705, 2024).
tumor (continued). "Notably, SYVN1 knockdown greatly reduced the tumour volume and tumour growth rate, as indicated by reduced Ki-67 staining." (PMID 37816756, 2023). "We next evaluated the effects of SYVN1 on tumor growth in vivo." (PMID 37099251, 2023). "In addition, sh-SYVN1 significantly reduced tumor regression rate, and the addition of immunocyte mixtures further decreased the tumor regression rate." (PMID 37099251, 2023). "Additionally, using a human ovarian granulosa-like tumor (KGN) cell line, we also confirmed that downregulated SYVN1 is associated with increased apoptosis and increased mitochondrial fission." (PMID 36193086, 2022). "Similarly, sh-SYVN1 or immunocyte mixtures reduced the percentage of Ki-67+ cells; however, the proportion of Ki-67+ cells was much lower in sh-SYVN1 + immunocyte mixture groups, suggesting that sh-SYVN1 or/and immunocyte mixtures decreased tumor cell proliferation." (PMID 37099251, 2023). "The findings indicating that miR-432 may exert a tumor suppressor effect by regulating SYVN1." (PMID 35543347, 2022). "Both SYVN1 and EGFR were expressed at higher levels in tumor tissues compared to normal tissues, as determined by Western blot." (PMID 40877231, 2025). "Next, we detected the protein expression levels of SYVN1 and EGFR, as well as the correlation between SYVN1 expression and the progression of NSCLC in pairs of tumor specimens." (PMID 40877231, 2025). "More importantly, we found that knockdown of SYVN1 resulted in a faster attenuation of EGFR signaling activity, which is detrimental to the rapid proliferation of tumor cells." (PMID 40877231, 2025). "To verify the exact role of SYVN1 in NSCLC progression, we overexpressed or knocked down SYVN1 in NSCLC cells and observed its effects on cell proliferation and tumor growth." (PMID 40877231, 2025). "Further investigations revealed that circSIRT5 promotes the ubiquitination and degradation of PHGDH by forming the circSIRT5/SYVN1/PHGDH ternary complex, thereby facilitating ferroptosis in BC cells and acting as a tumor suppressor." (PMID 39223162, 2024). "SYVN1 depletion upregulated the proportion of cytotoxic CD8 + T cells, which further potentiated the anti-tumor effects of CD8 + T cells." (PMID 37099251, 2023). "Immunoblotting analysis of key proteins in the excised tumor tissue revealed significant downregulation of MNK1, accompanied by a decrease in p-eIF4E, which can be attributed to elevated levels of SYVN1 compared to the control." (PMID 37766871, 2023). "Compared with the tumours that exhibited high SYVN1 expression, the PLA signal of ubiquitylation of MCT4 was significantly decreased in tissues with low SYVN1 expression." (PMID 37816756, 2023). "MCT4 ubiquitylation by SYVN1 promotes glycolysis and proliferation of LUAD cells in vitro and tumour growth in vivo, finally leading to tumour progression." (PMID 37816756, 2023). "Biochemical analyses confirmed the presence of elevated levels of SYVN1 protein in both VNLG-152R-treated cells in vitro and tumor tissues from the treated mice." (PMID 37766871, 2023). "SYVN1 and DERL1 were also significantly overexpressed in tumor tissues in the TCGA-ESCA dataset, indicating the significance of the overexpression of ERAD machinery in ESCC." (PMID 37444412, 2023). "To understand the role of SYVN1 in the apoptosis of GCs in PCOS, we used the human ovarian granulosa-like tumor (KGN) cell line." (PMID 36193086, 2022). "However, our study proposed that SYVN1 may be a tumor suppressor that target HMGB1 for degradation." (PMID 34820329, 2021). "In lung cancer, SYVN1 ubiquitylation degrades substrates such as SIRT2 and ATG3, and it also regulates the membrane localization of the MCT4 protein to promote tumor progression." (PMID 40877231, 2025). "Our results also showed that overexpression of SYVN1 could suppress proliferation, migration, and invasion in PTC cell lines and inhibit tumorigenesis in vivo, indicating that SYVN1 plays a tumor-suppressive role in PTC." (PMID 38679705, 2024).
tumor (continued). "Since SYVN1-mediated ubiquitylation regulates MCT4 activity, nuclear magnetic resonance (NMR) analysis was performed to examine the metabolic impacts of SYVN1 on xenograft tumour samples." (PMID 37816756, 2023). "Accordingly, knockdown of SYVN1 suppresses glycolysis and lactate export, which is supported by histological data in which concurrence of SYVN1 expression occurred with MCT4 ubiquitylation and lactate concentrations in tumour samples from NSCLC patients." (PMID 37816756, 2023). "Because SYVN1 has been shown to act as a tumor suppressor in TNBC models, in vitro and in vivo, we propose that this phenomenon may also contribute to the anti-tumor efficacy of our compounds." (PMID 37766871, 2023). "Although differences between the two viruses were not significant, SYVN1 silencing appeared to elicit a more immediate tumor growth inhibition." (PMID 36499754, 2022). "In this study, we identified that KDM4D/SYVN1 axis could modulate the post-transcriptional regulation of HMGB1, providing novel insights on HMGB1 accumulations in tumor." (PMID 34820329, 2021). "Interestingly, there are also other non-canonical substrates of SYVN1 which are known to play a crucial role in tumor progression." (PMID 37444412, 2023).
cancer (20 papers, 2015 to 2026). A tumor composed of atypical neoplastic, often pleomorphic cells that invade other tissues. "This work reveals a previously uncharacterized modification of MCT4 in LUAD and undescribed functions of SYVN1 in cancer metabolism." (PMID 37816756, 2023). "Inhibition of SYVN1 expression resulted in suppression of cancer growth, invasion and migration in hepatocellular carcinoma through an increase in expression of PTEN (Phosphatase and Tensin Homolog)." (PMID 33113804, 2020). "Recent studies have found that SYVN1 plays distinct roles in various cancers." (PMID 40877231, 2025). "Thus, the role of SYVN1 in tumourigenesis and cancer development is paradoxical and dependent on the cellular environment and microenvironment." (PMID 38679705, 2024). "E3 ubiquitin ligase synoviolin (SYVN1) has been reported to participate in many human cancers." (PMID 38679705, 2024). "This study adds LUAD to the growing list of human cancers that involve SYVN1." (PMID 37816756, 2023). "Our observations do, however, suggest that treatment of certain cancers with oncolytic adenoviruses could be made more effective by silencing SYVN1 and confirm the utility of combining oncolytic adenoviruses with RNAi." (PMID 36499754, 2022). "Enhanced killing of adenovirus-infected cancer cells due to SYVN1 silencing could perhaps interfere with virus propagation, if cell death is induced before the production of infectious progeny virus is completed." (PMID 36499754, 2022). "AdΔ24E3-U6.shSYVN1 was characterized for expression of mature SYVN1 siRNA in infected cancer cells." (PMID 36499754, 2022). "This suggests that oncolytic adenoviruses armed with a silencing cassette against SYVN1 might be applicable for virotherapy of a variety of different cancers." (PMID 36499754, 2022). "The ability of SYVN1 to modulate EGFR localization and activity presents a unique mechanism by which cancer cells can evade therapeutic interventions." (PMID 40877231, 2025). "In contrast, silencing SYVN1, but not irrelevant control siRNA, reproducibly and selectively increased adenovirus cancer-cell-killing potency." (PMID 36499754, 2022). "There are also reports on cancer cell invasion and metastasis of PANX1 and SYVN1." (PMID 33113804, 2020). "Interestingly, an RNAi screen for efficient cancer cell killing by a rhabdovirus identified several components of the ER stress response pathway, albeit not including SYVN1." (PMID 36499754, 2022). "However, the molecular mechanism of SYVN1 in cancer progression is not fully clarified." (PMID 38679705, 2024).
infection (13 papers, 2014 to 2026). The state of being infected such as from the introduction of a foreign agent such as serum, vaccine, antigenic substance or organism. "SYVN1 siRNA was produced in cells infected with AdΔ24E3-U6.shSYVN1 over the first 24 h after infection; thereafter, it remained present for at least more than a day." (PMID 36499754, 2022).
retinopathy (1 paper, 2017). "In retinopathy, SYVN1, syniviolin 1, is involved in endoplasmic reticulum associated degradation." (PMID 28761062, 2017).
SYVN1 also shares sentences with these, for which no sentence is quoted: Alzheimer disease (7 papers); neurodevelopmental disorder (6); neurodegenerative disease (5); acute kidney injury (4); developmental delay (4); Hepatic steatosis (4); Insulin resistance (4); microcephaly (4); Parkinson disease (4); viral infection (4); gastric cancer (3); Intellectual disability (3); prostate carcinoma (3); Arthritis (2); Autoimmunity (2); bacterial infection (2); cardiac hypertrophy (2); Central diabetes insipidus (2); Cirrhosis (2); diabetic kidney disease (2); epilepsy (2); ischemia (2); kidney disease (2); metabolic disorders (2); multiple sclerosis (2); pancreatic cancer (2); pancreatic ductal adenocarcinoma (2); parasitemia (2); psoriasis vulgaris (2); spinal cord ischemia (2).
A further 56 diseases each share a sentence with SYVN1 in 2 papers or fewer.